ABCE1 (ATP binding cassette subfamily E member 1)
Diseases named in the same sentence as ABCE1 in open-access papers (continued):
Sharing a sentence is not in itself a finding about the gene and the disease.
glioma (3 papers, 2018 to 2022). A benign or malignant brain and spinal cord tumor that arises from glial cells (astrocytes, oligodendrocytes, ependymal cells). "ATP-binding cassette transporter (ABCE1), being a chaperone, associates with chemotherapy resistance in glioma via PI3K/Akt/NF-κB pathway form PPIs with EBP and FDPS enzymes." (PMID 34440098, 2021). "Down-regulation of ABCE1 inhibited temozolomide (TMZ) resistance of glioma cells in vitro and in vivo." (PMID 30455394, 2018). "Our results suggested a promising therapeutic potential of ABCE1 in improvement of the chemotherapeutic outcome during glioma treatment." (PMID 30455394, 2018). "We also performed flow cytometry to detect the effect of ABCE1 down-regulation on glioma cell apoptosis induced by chemotherapy." (PMID 30455394, 2018). "In conclusion, our data showed that ABCE1 was critical in regulation of glioma sensitivity to TMZ and the PI3K/Akt/NF-κB pathway participated in the regulation." (PMID 30455394, 2018). "The results indicated that inhibition of the PI3K/Akt/NF-κB pathway by LY294002 (Akt inhibitor) and PDTC (NF-κB inhibitor) potentiated the suppressive effect of ABCE1 down-regulation on TMZ resistance in glioma cells." (PMID 30455394, 2018). "The data showed that ABCE1 expression in glioma tissues was significantly higher than that in the normal brain tissues at both mRNA and protein levels." (PMID 30455394, 2018). "To reveal the effect of ABCE1 on glioma, we detected the expression levels of ABCE1 in 38 pairs of glioma tissues and matched normal brain tissues by RT-PCR and Western blot analysis." (PMID 30455394, 2018). "In the present study, we examined the expression pattern of ABCE1 in glioma and tested the effect of ABCE1 knockdown on glioma sensitivity to TMZ." (PMID 30455394, 2018). "Taken together, our study suggested ABCE1 as a promising target for glioma chemotherapy." (PMID 30455394, 2018). "We found that ABCE1 expression was elevated in glioma tissues and cell lines." (PMID 30455394, 2018). "Moreover, we observed that ABCE1 down-regulation significantly inhibited TMZ resistance of glioma cells in vitro and in vivo." (PMID 30455394, 2018). "In the present study, we examined the expression pattern and possible role of ABCE1 in glioma." (PMID 30455394, 2018). "Our study demonstrated that ABCE1 was up-regulated in glioma tissues and cell lines." (PMID 30455394, 2018). "Down-regulation of ABCE1 inhibited TMZ resistance of glioma cells in vitro and in vivo." (PMID 30455394, 2018). "In addition, we found that the PI3K/Akt/NF-κB pathway was involved in ABCE1-mediated chemoresistance of glioma cells." (PMID 30455394, 2018). "Previous studies have revealed that the PI3K/Akt signaling pathway is frequently activated during glioma progression and its downstream target NF-κB is a well-known contributor to chemoresistance, thus we examined the effect of ABCE1 down-regulation on the PI3K/Akt/NF-κB pathway." (PMID 30455394, 2018). "We validated the expression levels of ABCE1 in two glioma cell lines." (PMID 30455394, 2018). "In addition, PI3K/Akt/NF-κB signaling pathway could be inactivated by ABCE1 depletion to enhance the sensitivity of glioma cells to TMZ." (PMID 35505656, 2022). "Our study results showed that down-regulation of ABCE1 significantly reduced the protein expression of p-PI3K, p-Akt, and NF-κB in glioma cells." (PMID 30455394, 2018). "However, there have been no investigations on the specific role of ABCE1 in glioma." (PMID 30455394, 2018). "However, there have been no investigations on the specific effect of ABCE1 on glioma." (PMID 30455394, 2018).
prostate carcinoma (3 papers, 2014 to 2024). A carcinoma that arises from epithelial cells of the prostate gland. "As an RNase L inhibitor, ABCE1 may be implicated directly or indirectly in prostate cancer formation and/or metastasis." (PMID 25070080, 2014). "Our results show a close correspondence of increased RNase L activity with caspase-3 enzyme activity, as observed previously in prostate cancer cells with ABCE1 knockdown." (PMID 33670646, 2021).
HIV-1 infection (2 papers, 2021). The type species of lentivirus and the etiologic agent of acquired immunodeficiency syndrome (AIDS). "Thus, this novel antiretroviral compound colocalizes with HIV-1 Gag and with the host proteins ABCE1 and DDX6, all of which are components of HIV-1 assembly intermediates, and colocalizes with ABCE1 and DDX6 even in the absence of HIV-1 infection." (PMID 33148797, 2021). "Interestingly, our studies found that PAV-206 colocalizes with both of these host enzymes, ABCE1 and DDX6, in the absence of HIV-1 infection, suggesting that the compound acts on the host RNA-granule-related RNP complex that is the precursor of assembly intermediates, even in the absence of Gag." (PMID 33148797, 2021).
leukaemia (2 papers, 2023 to 2024). "Even though in most tumorigenesis and doxorubicin drug resistance, P-gp is the pioneer reprehensive of ABC transporters targeted by miRNAs, in leukaemia, some other little-known members comprising of ABCE1, ABCC5, and ABCC10 have been inferred in this process." (PMID 39679367, 2024). "miR-145 and miR-181 promote apoptosis of leukemia stem cells through regulation of ABCE1 and MCL-1 respectively, and miR-424 inhibits BCR-ABL activity." (PMID 37476380, 2023). "Notably, similar to the role of ABCC5 and ABCC10 in modulating proliferation and apoptosis in leukaemia, ABCE1 knockdown significantly suppressed H69/ADR cell growth, augmented the cell cycle inhibition rate, and promoted apoptosis." (PMID 39679367, 2024). "miRNAs have the utmost importance in overcoming chemoresistance in leukaemia by targeting ABC transporters like P-gp and others, such as ABCE1, ABCC5, and ABCC10." (PMID 39679367, 2024).
lung adenocarcinoma (2 papers, 2012 to 2018). A carcinoma that arises from the lung and is characterized by the presence of malignant glandular epithelial cells. "Subsequently, we constructed lentiviral vectors containing ABCE1-specific shRNA and infected human lung adenocarcinoma A549 cells to supress ABCE1 expression." (PMID 22267055, 2012). "To probe the potential function of ABCE1 in lung adenocarcinoma, we performed microarray analysis to find the differentially expressed genes after ABCE1 silence." (PMID 22267055, 2012). "Our study showed, with the advancement of clinical stages of lung adenocarcinoma, ABCE1 mRNA and protien expression were increased." (PMID 22267055, 2012). "Collectively, our results demonstrated abnormal expression of ABCE1 gene in human lung adenocarcinoma and its effect in the proliferation of lung adenocarcinoma cells." (PMID 22267055, 2012). "In the present study, we found a high expression level of ABCE1 mRNA and protein in human lung adenocarcinoma tissues and metastatic lymph nodes, which was also correlated with clinical stages." (PMID 22267055, 2012). "Subsequently, we analyzed the association between the clinical stages (classified according to the 1997 TNM classification of UICC) and ABCE1 expression of the 18 cases of lung adenocarcinoma." (PMID 22267055, 2012). "The human lung adenocarcinoma A549 cells were infected with lentiviral vectors containing ABCE1-specific shRNA, and resulted in significant inhibition of cell growth." (PMID 22267055, 2012). "Lentiviral vectors containing ABCE1-specific shRNA were constructed and human lung adenocarcinoma A549 cells were infected." (PMID 22267055, 2012). "The results of RT-PCR and Western blot analysis showed that ABCE1 mRNA and protein were expressed in lung adenocarcinoma tissues, normal lung tissues and metastatic lymph nodes." (PMID 22267055, 2012). "In the present study, we aimed at assessing the role of ABCE1 in the development and progress of human lung adenocarcinoma." (PMID 22267055, 2012). "We first detected the expression of ABCE1 mRNA and protein in lung adenocarcinoma tissues and metastatic lymph nodes." (PMID 22267055, 2012). "To probe the role of ABCE1 gene in human lung adenocarcinoma, we first detected its expression in human lung adenocarcinoma tissues." (PMID 22267055, 2012). "Our results demonstrated the potential role of ABCE1 in the development and progress of human lung adenocarcinoma." (PMID 22267055, 2012). "In the present study, to probe the role of ABCE1 in human lung adenocarcinoma, we first detected its mRNA and protein expression in tissues." (PMID 22267055, 2012). "Our results demonstrated the potential role of ABCE1 in human lung adenocarcinoma, which may provide some molecular basis for the mechanisms of development and progress of human lung adenocarcinoma, and help to find new pharmacological targets." (PMID 22267055, 2012). "Subsequently, to assess the function of ABCE1 in lung adenocarcinoma, we carried out siRNA assay." (PMID 22267055, 2012). "Moreover, human lung adenocarcinoma A549 cells were infected with lentiviral vectors containing ABCE1-specific shRNA, and resulted in significant inhibition of cell growth." (PMID 22267055, 2012).
oral cancer (2 papers, 2024 to 2025). "However, differential expression was observed with TRIM2, ADD3, and ABCE1 among some of the oral cancer cell lines." (PMID 38396844, 2024). "ABCE1 expression was found to be low in adjacent non-tumor tissues but high in oral cancer; there was an inverse relationship between ABCE1 expression and the degree of cancer cell differentiation." (PMID 40362545, 2025).
small cell lung carcinoma (2 papers, 2014 to 2021). Small cell lung cancer (SCLC) is a highly aggressive malignant neoplasm, accounting for 10-15% of lung cancer cases, characterized byrapid growth, and early metastasis. "ABCE1 has previously been reported to be involved in the development of small cell lung cancer and lung adenocarcinoma." (PMID 25070080, 2014). "The ABCE1 gene has been reported to be overexpressed in numerous tumors, including colon, rectal, lung and small cell lung cancer." (PMID 25070080, 2014).
bladder cancer (1 paper, 2024). "In our studies, we found a high expression of ABCE1 in muscle-invasive high-grade bladder cancer tissues compared to normal bladder tissues." (PMID 39315278, 2024). "In addition, primary bladder cancer cells and patient-derived glioblastoma cells showed high expression of ABCE1." (PMID 39315278, 2024). "The levels of RQC proteins ZNF598, NEMF, and ABCE1 induced by EME was decreased by co-treatment with CCCP in T24 and primary culture bladder cancer cells." (PMID 39315278, 2024).
brain tumor (1 paper, 2024). "ABCE1 OE also partially rescued Notch-induced brain tumor phenotype, and Nsp1/ABCE1 co-expression, which synergistically down-regulated dMyc translation as in cMyc case in mammalian cells, resulted in a more complete inhibition of Notch-induced NB overgrowth." (PMID 39161732, 2024). "As in Notch-induced brain tumor condition, co-expression of Nsp1 and ABCE1 further enhanced the Nsp1 effect in inhibiting InR-induced eye overgrowth." (PMID 39161732, 2024).
glioblastoma (1 paper, 2024). The most malignant astrocytic tumor (WHO grade IV). "To test the role of ABCE1 in mitochondrial homeostasis, we overexpressed an ABCE1-FLAG plasmid in LN299 glioblastoma cells." (PMID 39315278, 2024).
iron deficiency (1 paper, 2021). "It is tempting to speculate that C. glabrata may increase the expression of Dom35 and Hbs1 to compensate for potential translation termination defects caused by a decrease in the activity of ABCE1/Rli1 during iron deficiency." (PMID 34068342, 2021).
iron overload (1 paper, 2020). "The impact of PINK1 mutations in mouse and patient cells was pronounced only after iron overload, causing hyperreactive expression of ribosomal surveillance factor Abce1 and of ferritin, despite ferritin translation being repressed by IRP1." (PMID 33023155, 2020).
lung squamous cell cancer (1 paper, 2020). "LncRNA FAM201A mediates the metastasis of lung squamous cell cancer via regulating ABCE1 expression." (PMID 32976115, 2020).
medulloblastoma (1 paper, 2020). A malignant, invasive embryonal neoplasm arising from the cerebellum. "The known MYC target gene, ABCE1, doesn’t show any significant co-expression correlation in Medulloblastoma." (PMID 31932624, 2020).
pneumonia (1 paper, 2013). An acute, acute and chronic, or chronic inflammation focally or diffusely affecting the lung parenchyma, caused by an infection in one or both of the lungs (by bacteria, viruses, fungi, or mycoplasma.). "Other genes related to protein synthesis (ribosomal proteins and other eukaryotic initiation factors) and the unfolded protein response (a stress response to excessive protein synthesis), were also significantly under-abundant in the pneumonia patients e.g. PERK, CHOP, ABCE1 (data not shown)." (PMID 23940611, 2013).
retinoblastoma (1 paper, 2025). A malignant tumor that originates in the nuclear layer of the retina. "In a study conducted on the effect of genistein on retinoblastoma, it was observed that genistein reduces the expression of ABCE1 by inducing the expression of miR-145, ultimately inhibiting the growth of cancer cells." (PMID 40718456, 2025).
thyroid cancer (1 paper, 2018). "In thyroid cancer, ABCE1 was demonstrated to enhance cell viability and invasion in vitro." (PMID 30455394, 2018).
cancer (22 papers, 2012 to 2026). A tumor composed of atypical neoplastic, often pleomorphic cells that invade other tissues. "ABCE1 has also been implicated in cancer progression, particularly in lung and breast cancer, where its overexpression correlates with tumor growth and metastasis." (PMID 40785597, 2025). "The chromosomic localization of the ABCE1 gene is a fragile site already associated with structural rearrangements in cancers." (PMID 34440115, 2021). "In fact, ABCE1 overexpression has been associated with the tumorigenic process of several human cancers, for instance, lung cancer, breast cancer, esophageal cancer, ovarian cancer, and glioma." (PMID 34440115, 2021). "There is substantial evidence that ABCE1 is closely associated with the regulation of cancer cell growth, migration and invasion and is involved in promoting cell proliferation, differentiation and protein synthesis." (PMID 25815591, 2015). "The tumor growth-promoting functions of the miR-96 and ABCE1 could be partially mediated by the crosstalk between tumor cells and cancer associated fibroblasts (CAFs), which we found to be downregulated in miR-96 OE and Abce1 KD groups compared to Scrambled." (PMID 30305609, 2018). "Previous studies have demonstrated that ATP-binding cassette protein E1 (ABCE1) is important in tumor development and abnormal expression may be associated with malignant tumor proliferation and migration." (PMID 25815591, 2015). "As ABCE1 is essential for translation initiation, and translation is a highly regulated process important to development and pathologies of cancer, tumor cells are thought to be more sensitive to the ABCE1 loss of function, making ABCE1 a potential target for therapeutics." (PMID 22267055, 2012). "Here we show that the oncogenic overexpression of the RNase L inhibitor ABCE1, a component of interferon signalling, leads to distinct and extensive deviations in cancer transcriptomes." (PMID 41663214, 2026). "Our results show that ribosome stalling during heightened cMyc translation and the up-regulated expression of translation factors such as ABCE1 by cMyc present vulnerabilities in cMyc-driven cancers that can be targeted by Nsp1 through the ZNF598 RQC pathway." (PMID 39161732, 2024). "Our study highlights the significance of mitochondrial entrapment of RQC factors such as ABCE1 in determining the fate of cancer cells versus CSCs." (PMID 39315278, 2024). "The synergy between Nsp1 and ABCE1 in down-regulating cMyc and inhibiting cancer cell growth is unexpected, as ABCE1 tends to be up-regulated in cancer cells and its supporting role in oncogenesis has been observed in multiple cancer settings." (PMID 39161732, 2024). "Our analysis of human cancer gene expression in Pan-cancer analysis of whole genomes (ICGC/TCGA) revealed that the expression of c-Myc positively correlated with that of ABCE1." (PMID 39161732, 2024). "ABCE1 expression was further investigated in tumor–tissue derived bulk cancer population and cancer stem cell population." (PMID 39315278, 2024). "In this study, we investigated the function of ABCE1 using patient-derived primary cultured cancer cell models." (PMID 39315278, 2024). "ABCE1 is recognized as a marker of drug resistance and plays a crucial role in the survival of cancer cells." (PMID 39315278, 2024). "EME treatment led to increased levels of RQC proteins ZNF598 and ABCE1 at early time points in both T24 and primary cultured cancer cells." (PMID 39315278, 2024). "We found that ABCE1 interacted with Nsp1 in cancer cells as detected by co-immunoprecipitation (co-IP) assay." (PMID 39161732, 2024). "As a novel therapeutic tool, Nsp1 acts through at least two mechanisms to perturb cMyc-driven cancer growth: inhibition of cMyc expression, and synthetic lethality with genes up-regulated by cMyc (e.g. ABCE1)." (PMID 39161732, 2024).